HDAC11 (histone deacetylase 11)
Diseases named in the same sentence as HDAC11 in open-access papers (continued):
Sharing a sentence is not in itself a finding about the gene and the disease.
infection (3 papers, 2014 to 2023). The state of being infected such as from the introduction of a foreign agent such as serum, vaccine, antigenic substance or organism. "Moreover, the ratio of HDAC11-S4 RNA 4, S4 RNA, and HDAC11 RNA in BmCPV-infected BmN cells at 48 h post-infection was estimated using RT-qPCR, and the results showed that HDAC11-S4 RNA4: S4 RNA: HDAC11 was 1:19:139, indicating that only a fraction of S4 RNA and HDAC11 RNA become chimeric RNAs." (PMID 38048361, 2023). "Consistently, HDAC11-mediated deacetylation among H3K9ac and H3K27ac also inhibits HBV transcription and replication in HBV-transfected and HBV in vitro infection systems." (PMID 35468873, 2022). "In contrast, genes in a cluster known to regulate nucleoplasm architecture such as HDAC11, CCNE2, and POLI reduced infection upon depletion." (PMID 24874089, 2014).
cardiovascular diseases (2 papers, 2022 to 2025). "Among the human zinc-dependent HDACs, the most recently discovered member, HDAC11, has been shown to play a role in cardiovascular diseases through promoting inflammation." (PMID 35279683, 2022). "Histone deacetylase 11 (HDAC11), a sole member of the class IV HDAC subfamily, participates in various cardiovascular diseases." (PMID 35279683, 2022). "Histone deacetylase 11 (HDAC11), the only class IV HDAC member, is reported to regulate immune activation, tumorigenesis, and cardiovascular diseases." (PMID 35279683, 2022).
adenocarcinoma (1 paper, 2022). A common cancer characterized by the presence of malignant glandular cells. "Hdac11 was dramatically decreased in the “inflammation-adenocarcinoma” tissues compared with the expression level in normal colorectal tissue, on the contrary, expression level of Mmp3 was increased." (PMID 35399729, 2022). "The protein levels of Hdac11 and Mmp3 were investigated by immunohistochemistry in normal, inflammation and adenocarcinoma colon tissues of the CAC mouse model, which was consistent with the qRT-PCR result." (PMID 35399729, 2022).
inflammation (1 paper, 2022). Aberrant reaction of the microcirculation characterized by movement of fluid and leukocytes from the blood into extravascular tissues. "have revealed that HDAC11 could inhibit IL-10 expression and induce inflammatory antigen-presenting cells, showing agreement with the positive correlation between HDAC11 and mild chronic inflammation in some degree." (PMID 36324577, 2022).
neurological disease (1 paper, 2018). "Finally, higher HDAC11 transcript levels were reported in female patients with MS, implicating a clinical significance of HDAC11 in this neurological disease." (PMID 30456376, 2018).
psychiatric disease (1 paper, 2017). "HDAC11 may have a more general association with psychiatric disease." (PMID 28928414, 2017).
HDAC11 also shares sentences with these, for which no sentence is quoted: fatty liver disease (3 papers); chronic renal disease (2); kidney diseases (2); status epilepticus (2); Ureteral obstruction (2); uveal melanoma (2); anaplastic oligodendroglioma (1); autoimmune disease (1); bipolar disorder (1); brain disorder (1); endothelial dysfunction (1); fibrosis (1); immune disorders (1); lentivirus infection (1); liver steatosis (1); lung (1); lung disease (1); monoclonal gammopathy of undetermined significance (1); oligodendroglioma (1); pancreatic adenocarcinoma (1); pancreatic cancer (1); pituitary tumor (1); renal pelvis urothelial carcinoma (1); retinal diseases (1); squamous cell carcinoma (1); viral infections (1).